DPP4 (dipeptidyl peptidase 4)
Diseases named in the same sentence as DPP4 in open-access papers (continued):
Sharing a sentence is not in itself a finding about the gene and the disease.
central obesity (4 papers, 2019 to 2025). "Although unfortunately not included in the observations, the adoption of a visceral fat area or abdominal obesity indices may have helped to identify more clearly those individuals for whom DPP4 inhibitors improved vascular function." (PMID 38256615, 2024). "In addition, DPP-4 expression was shown to positively correlate with the extent of central obesity, visceral adiposity, and inflammation." (PMID 35054972, 2022).
cervical cancer (4 papers, 2015 to 2020). A primary or metastatic malignant neoplasm involving the cervix. "By integrated bioinformatics analysis of cervical cancer datasets from the Gene Expression Omnibus (GEO), DPP4 and SFRP4 were identified among the 8 top downregulated hypermethylated tumor suppressor genes." (PMID 32899940, 2020). "For instance, reduced level of DPP4 (CD26) expression/activity was detected in HPV(+) cervical cancer cell lines compared to non-cancerous cell lines." (PMID 32899940, 2020).
cholangiocarcinoma (4 papers, 2021 to 2025). A carcinoma that arises from the intrahepatic biliary tree (intrahepatic cholangiocarcinoma) or from the junction, or adjacent to the junction, of the right and left hepatic ducts (hilar cholangiocarcinoma). "We used nationwide registers in three Scandinavian countries to conduct two cohort studies that assessed the risk of cholangiocarcinoma associated with use of DPP4 inhibitors and GLP-1-receptor agonists, respectively." (PMID 34254177, 2021). "The study found that use of DPP4 inhibitors, compared with other second- or third-line glucose-lowering drugs, was associated with a 77% increase in the risk of cholangiocarcinoma (HR 1.77 [95% CI 1.04, 3.01]), although the analysis only included 27 DPP4 inhibitor-exposed events." (PMID 34254177, 2021). "A recent meta-analysis identified three clinical trials of DPP4 inhibitors in which at least one case of cholangiocarcinoma was reported; three and four events occurred among patients receiving DPP4 inhibitors and placebo, respectively." (PMID 34254177, 2021). "Concerns have been raised regarding a potential association of use of the incretin-based drugs dipeptidyl peptidase 4 (DPP4) inhibitors and glucagon-like peptide-1 (GLP-1)-receptor agonists with risk of cholangiocarcinoma." (PMID 34254177, 2021). "To provide further data on this safety concern, we used nationwide registers in Sweden, Denmark and Norway to assess the association of use of DPP4 inhibitors and GLP-1-receptor agonists with risk of cholangiocarcinoma." (PMID 34254177, 2021). "In the analyses in which the exclusion criteria related to risk factors of cholangiocarcinoma were not applied, the adjusted HR vs sulfonylureas was 1.15 (95% CI 0.91, 1.45) for DPP4 inhibitors and 1.19 (95% CI 0.85, 1.66) for GLP-1-receptor agonists." (PMID 34254177, 2021). "During 1,414,144 person-years of follow-up, cholangiocarcinoma occurred among 222 patients with use of DPP4 inhibitors (incidence rate, 26 per 100,000 patient-years) and among 128 patients with use of sulfonylureas (incidence rate, 23 per 100,000 patient-years)." (PMID 34254177, 2021). "We used data from nationwide registers in Sweden, Denmark and Norway, 2007–2018, to conduct two cohort studies, one for DPP4 inhibitors and one for GLP-1-receptor agonists, to investigate the risk of incident cholangiocarcinoma compared with an active-comparator drug class (sulfonylureas)." (PMID 34254177, 2021). "In conclusion, in this study using nationwide data from three Scandinavian countries and sulfonylureas as the comparator, neither use of DPP4 inhibitors nor use of GLP-1-receptor agonists was associated with a significantly increased risk of cholangiocarcinoma." (PMID 34254177, 2021).
cutaneous T-cell lymphoma (4 papers, 2021 to 2024). "Likewise, further analyses employing larger patient cohorts might help to further refine the diagnostic value of CD26/DPP4 expression in cutaneous T-cell lymphoma and to assess its suitability as a prognostic factor." (PMID 34885056, 2021). "Due to their remarkable tumoricidal properties CD26-positive T cells are considered promising candidates for T cell-based immunotherapies while in cutaneous T cell lymphoma CD26/DPP4 expression patterns are established markers for diagnosis and possibly prognosis." (PMID 34885056, 2021). "Moreover, especially in cutaneous T-cell lymphoma CD26/DPP4 expression patterns emerged as an established marker for diagnosis and treatment monitoring." (PMID 34885056, 2021).
diabetic foot ulcers (4 papers, 2018 to 2025). "Animal experiments and clinical studies have indicated that DPP‐4 inhibitors can increase circulating levels of EPCs and potentially facilitate the healing of diabetic foot ulcers (DFUs); however, these findings remain preliminary and are subject to debate." (PMID 40948240, 2025). "The effect of combined insulin and dipeptidyl peptidase-4 inhibitor (DPP4i) therapy on major adverse cardiovascular events (MACEs) in patients with diabetic foot is unclear." (PMID 30349614, 2018).
endometriosis (4 papers, 2019 to 2025). The growth of functional endometrial tissue in anatomic sites outside the uterine body. "Consistent with the RNASeq results, pathway analysis revealed that proteins involved in collagen metabolic processes, such as Serpin H1, α-N-Acetylglycosaminidase, and DPP4, were significantly enriched in ESCs from deep and superficial endometriosis." (PMID 41369380, 2025).
glomerular disease (4 papers, 2019 to 2024). "In the present study, glomerular DPP-4 activity was enhanced in glomerular diseases, while basal DPP-4 expression on parietal epithelial cells in Bowman’s capsules and proximal tubules was detected." (PMID 32948146, 2020). "The present study demonstrated that glomerular DPP-4 is activated in glomerular diseases, such as DN, FSGS, and ANCA-RN." (PMID 32948146, 2020). "The present study revealed that DPP-4 activity was increased in human podocytes of glomerular diseases." (PMID 32948146, 2020). "DPP-4 inhibitors may be useful for developing treatments for glomerular disease with podocyte injury." (PMID 32948146, 2020). "Additionally, podocytes may be the target cells of DPP-4 inhibitors and targets for therapeutic applications of saxagliptin for some glomerular diseases." (PMID 32948146, 2020). "DPP-4 was clearly detected in the proximal tubules and Bowman’s capsule, but not in the distal tubules and interstitial tissues of any glomerular disease." (PMID 32948146, 2020).
Graves disease (4 papers, 2021 to 2023). Graves' disease is an autoimmune disorder that leads to overactivity of the thyroid gland (hyperthyroidism).It is caused by an abnormal immune system response that causes the thyroid gland to produce too much thyroid hormones. "A multicenter observational case–control study that included 80 patients with T2DM and Graves’ disease who were administered an oral hypoglycemic agent, including DPP-4 inhibitors, showed that there is a suggestive association between DPP-4 inhibitors and Graves’ disease exacerbation." (PMID 38004062, 2023). "However, a recent study observed decreased serum DPP4 levels in patients with Graves’ disease or Graves’ ophthalmopathy (GO), which is inconsistent with our findings." (PMID 37350750, 2023).
hypothyroidism (4 papers, 2016 to 2022). Abnormally low levels of thyroid hormone. "In the multivariable regression analysis, hypothyroidism, inappropriate alcohol use, treatment with a DPP-4 inhibitor and a combination of GLP-1 agonist with other oral antidiabetic drugs were associated with increased HbA1c after lockdown." (PMID 34575207, 2021). "In addition, we could identify hypothyroidism, inappropriate alcohol use, treatment with a DPP-4 inhibitor and a combination of GLP-1 agonist with other oral antidiabetic drugs as individual risk factors associated with an increase of HbA1c after the lockdown." (PMID 34575207, 2021).
infarction (4 papers, 2016 to 2023). A localised pathological necrosis of tissue resulting from obstruction of the blood supply usually by a thrombus, an embolus, or vascular torsion. "In addition to regulation of post-prandial glycaemia, DPP-4 inhibitors may have pleiotropic effects and may play a role in post-infarction arrhythmias." (PMID 26811539, 2016).
intestinal obstruction (4 papers, 2021 to 2025). Blockage of the normal flow of the intestinal contents within the bowel. "Lastly, in a large real-world study, GLP-1RA and dipeptidyl peptidase-4 inhibitors were associated with an increased risk of intestinal obstruction but this association was highest with 1.6–1.8 years of use." (PMID 40917760, 2025). "It should be appreciated that, in general, the use of DPP-4 inhibitors in these studies was associated with a higher risk of intestinal obstruction than GLP-1RAs." (PMID 39418085, 2024).
osteosarcoma (4 papers, 2017 to 2026). A usually aggressive malignant bone-forming mesenchymal neoplasm, predominantly affecting adolescents and young adults. "However, it has been reported that both NEP (CD10) and DPP-4 (CD26) are expressed at higher levels in human primary osteosarcoma bone tissues compared to adjacent noncancerous bone tissue, and that their combined expression correlates with poor prognosis." (PMID 36983138, 2023).
Peritoneal Fibrosis (4 papers, 2021 to 2024). Disorder characterized by a wide range of structural changes in PERITONEUM, resulting from fibrogenic or inflammatory processes. "Expression of DPP4 was increased in the thickening peritoneum of chlorhexidine gluconate-induced peritoneal fibrosis model of rats." (PMID 35309368, 2022). "This clinical observational study of PD patients has shown that DPP4 enzyme played a major role in peritoneal fibrosis and deterioration." (PMID 36579194, 2022). "One of the essential findings in the present study was that we identified the DPP4 played a key role in peritoneal fibrosis and dysfunction through promoting EMT, inflammation, and angiogenesis." (PMID 33514826, 2021). "This study provides mechanistic insights into the effects of DPP4 on peritoneal fibrosis and the translational potential of these effects." (PMID 33514826, 2021). "We believe our study provided solid data to establish the role of DPP4 in the pathogenesis of peritoneal fibrosis and explain the beneficial effects of DPP4 inhibitors fundamentally." (PMID 33514826, 2021). "Accordingly, to further explore the role of DPP4 and potential mechanism in peritoneal fibrosis, we investigated the molecular changes of mesothelial cells on a stepwise increment of glucose exposure." (PMID 33514826, 2021). "Furthermore, sitagliptin and exendin-4 treatments markedly inhibited DPP4 levels, resulting in ameliorating peritoneal fibrosis and functional impairment." (PMID 33514826, 2021). "In conclusion, our results of cell level and animal model studies, and clinical observational findings showed that DPP4 enzyme played a key contributor to the peritoneal fibrosis and functional impairment, whereas DPP4 inhibitors safeguarded PD from dysfunction and failure." (PMID 33514826, 2021). "Therefore, we first analyzed a 17-year observational data from Taiwan National Health Insurance Research Database to explore whether DPP4 inhibitor could inhibit chronic PD-induced peritoneal fibrosis and further reduce the rate of PD failure." (PMID 33514826, 2021). "In mice suffering from peritoneal fibrosis induced by MGO, administration of ligagliptin, which is a dipeptidyl peptidase-4 (DPP-4) inhibitor, blocked the infiltration of F4/80-positive macrophages and collagen deposition while improving peritoneal function." (PMID 39749340, 2024). "Therefore, the use of DPP4 inhibitors can help prevent the MMT and prevent peritoneal fibrosis as DPP4 inhibition holds antifibrotic effects." (PMID 36579194, 2022).
prostate adenocarcinoma (4 papers, 2014 to 2025). "Using the TIMER2.0 database, we explored the relationship between DPP4 expression and tumor-infiltrating immune cells in the prostate adenocarcinoma cohort (PRAD)." (PMID 40766751, 2025).
scleroderma (4 papers, 2020 to 2025). Scleroderma is a rare autoimmune connective tissue disorder characterized by abnormal hardening of the skin and, sometimes, other organs. "Here, immunostaining of human scleroderma skin sections showed that DPP4+THY1+ fibroblasts accumulated in the dermal interstitial spaces and at the interface between the dermis and hypodermal adipose tissue." (PMID 39072821, 2025). "Early research reported an increase in both absolute number and percentage of peripheral blood CD4+DPP4+T in scleroderma patients, and the levels of DPP4 expression in T cells correlated with disease activity." (PMID 35309368, 2022).
Sjögren’s syndrome (4 papers, 2021 to 2025). "In view 3of these observations, targeting DPP4 as a salivary biomarker in patients with Sjögren’s syndrome holds significant diagnostic and therapeutic potential." (PMID 41301757, 2025). "Studies conducted by Garreto and colleagues demonstrated that in the saliva of patients suffering from Sjögren’s syndrome, there is a significant increase in both the activity and concentration of dipeptidyl peptidase-4 (DPP4/CD26)." (PMID 41301757, 2025). "A case-control study found that salivary DPP4 activity was increased in the patients with Sjögren’s syndrome (SS), and there was a positive correlation between DPP4 activity and MMP9 level." (PMID 35309368, 2022).
skin cancer (4 papers, 2012 to 2025). "Furthermore, a meta-analysis of RCTs uncovered that DPP-4 inhibitor treatment was associated with a reduced risk of skin cancer in patients with T2D." (PMID 39640975, 2024). "Fourth, owing to the lack of reliable genetic tools, we were unable to evaluate the effects of certain antidiabetic drug target perturbations (such as INSR and DPP4) on skin cancer." (PMID 39640975, 2024). "Further, we found a higher expression of Cxcl9, Cxcl10, and Dpp4 in DCs in skin tumors." (PMID 40282557, 2025).
thrombosis (4 papers, 2020 to 2025). "We have not explored non-platelet mechanisms by which DPP-4 might regulate arterial thrombosis by directly affecting vascular wall cells." (PMID 33328991, 2020).
AIDS (3 papers, 2012 to 2020). A syndrome resulting from the acquired deficiency of cellular immunity caused by the human immunodeficiency virus (HIV). "A study on HIV infection provided evidence that immunomodulation by Ursodeoxycholic acid can increase the number of CD4+DPP4+ T cells in AIDS patients." (PMID 29987877, 2018). "In contrast, several laboratories have reported a selective decrease in DPP4-expressing T cells in AIDS progression, suggesting that DPP4 rendered the cells more sensitive to HIV-1 infection." (PMID 22291902, 2012).
aortic valve stenosis (3 papers, 2016 to 2025). Aortic valve stenosis (AVS) is a condition characterized by narrowing of the heart's aortic valve opening. "A combination diet with high-cholesterol and vitamin D (VitD) supplements has been shown to induce aortic valve stenosis and calcium deposition in rabbits and increase DPP-4 activity." (PMID 33401457, 2021).
autism spectrum disorder (3 papers, 2021). A spectrum of developmental disorders that includes autism, and Asperger syndrome. "The observed pattern agrees with the role of DPP4 in processing the neuropeptides substance P and NPY and immune response and the proposed association with autism spectrum disorders." (PMID 33834688, 2021). "Presumably, a high concentration of enzyme is not always correlated with high catalytic activity, which we described in our previous studies on the role of dipeptidyl peptidase-4 (DPPIV; EC 3.4.14.5) in autism spectrum disorders." (PMID 34772352, 2021).
autoimmune myocarditis (3 papers, 2015 to 2024). Autoimmune myocarditis is an autoimmune disease that affects the heart. "Two DPP-4 inhibitors suppress fibrosis and inflammation in experimental autoimmune myocarditis in mice." (PMID 39026189, 2024). "To clarify the effects of a DPP-4 inhibitor on myocarditis, we used an experimental autoimmune myocarditis (EAM) model in Balb/c mice." (PMID 25768281, 2015). "Thus, the aim of this study was to clarify the role of DPP-4 inhibitors in murine experimental autoimmune myocarditis (EAM)." (PMID 25768281, 2015). "In experimental autoimmune myocarditis (EAM), CTSG binds to Dipeptidyl Peptidase-4 (DPP-4) on T lymphocytes, enhancing its activity by inhibiting SerpinA3N." (PMID 39736788, 2024).
brain injuries (3 papers, 2025 to 2026). "According to studies, DPP-4 may cause neuronal damage and impair healing by triggering the inflammatory response after brain trauma." (PMID 41528544, 2026). "Further research is needed to explore the mechanisms linking DPP-4 inhibitors with EuDKA, especially in the context of metabolic stress like traumatic brain injury." (PMID 40725973, 2025). "DPP-4 inhibitors, including saxagliptin, have shown potential in reducing amyloid-β and tau pathologies, which are common in prolonged DOC and severe brain injuries." (PMID 39904872, 2025).
breast tumor (3 papers, 2013 to 2021). "The effects of 1,25(OH)2D3 0.5nM on the expression of CYP24A1, DPP4, IL1RL1, CD14, CA2 and BMP6, were further explored in breast tumor derived cells, representing the epithelial and stromal compartments, using RT-qPCR." (PMID 23497279, 2013).
carcinoid (3 papers, 2015 to 2021). "This temporal correlation suggests a possible interaction between the activity of carcinoid tumors and the use of DPP-4 inhibitors." (PMID 26290759, 2015). "With specific regard to the progression of carcinoid tumor and the use of DPP-4 inhibitors, we were not able to identify any reports in the literature." (PMID 26290759, 2015).
carotid atherosclerosis (3 papers, 2016 to 2023). A thickening and loss of elasticity of the walls of carotid arteries that occur with formation of atherosclerotic plaques. "In conclusion, our data suggested that DPP-4 inhibitors were associated with the regression of carotid atherosclerosis in insulin-treated T2DM patients free of apparent CVD." (PMID 28250768, 2017). "Our data suggested that DPP-4 inhibitors were associated with the regression of carotid atherosclerosis in insulin-treated T2DM patients." (PMID 28250768, 2017).
dilated cardiomyopathy (3 papers, 2016 to 2022). Cardiomyopathy which is characterized by dilation and contractile dysfunction of the left and right ventricles. "However, both GLP-1 analogues and DPP-4 inhibitors confer protection against cardiac dysfunction/remodelling associated with experimental MI, dilated cardiomyopathy, and hypertensive CHF in the absence of metabolic changes, indicating that GLP-1 exerts direct cardiac effects." (PMID 26597728, 2016).
gestational diabetes mellitus (3 papers, 2019 to 2024). "Furthermore, it was noted that there was a marked increase in DPP4-rich EVs in the blood of women with gestational diabetes mellitus (GDM)." (PMID 39239092, 2024). "Dipeptidyl peptidase-4 cleaves the glucagon-like polypeptide-1, which increases insulin secretion so that placental exosomes may be involved in the pathogenesis of gestational diabetes mellitus." (PMID 33671527, 2021).
head and neck cancer (3 papers, 2024 to 2025). A primary or metastatic malignant neoplasm affecting the head and neck. "It was also previously shown that patients suffering from head and neck cancer and had higher plasma DPP-4 level had better survival." (PMID 39390508, 2024).
hepatic insufficiency (3 papers, 2019 to 2022). "Dosage of DPP-4 inhibitors in renal and hepatic insufficiency." (PMID 31366085, 2019). "It is the only DPP-4 inhibitor that does not require dose adjustment in the treatment of DN, which has good hypoglycemic effects even in CKD stage 5 and can continue to be used in the presence of hepatic insufficiency." (PMID 36177313, 2022).